IL2RA (interleukin 2 receptor subunit alpha)
Description:
Receptor for interleukin-2. The receptor is involved in the regulation of immune tolerance by controlling regulatory T cells (TREGs) activity. TREGs suppress the activation and expansion of autoreactive T-cells.
Synonyms: CD25; IDDM10; IL2R; IMD41; TCGFR; p55
Tractability: Antibody: an approved drug acts on it; its Gene Ontology location is reachable by antibodies, with high confidence; UniProt predicts a signal peptide or a membrane-spanning region. PROTAC: a small molecule that binds it is known. Other modalities: an approved drug acts on it.
Target class: Membrane receptor
Gene: Protein-coding gene on chromosome 10 (6,010,689 to 6,062,370, reverse strand). Ensembl gene ENSG00000134460.
Subcellular location: Membrane
Pathways (Reactome):
Immune System: Interleukin receptor SHC signaling; Interleukin-2 signaling
Gene expression (Transcription): RUNX1 and FOXP3 control the development of regulatory T lymphocytes (Tregs)
Signal Transduction: RAF/MAP kinase cascade
Gene Ontology:
Molecular function: interleukin-2 receptor activity; protein binding; interleukin-2 binding
Biological process: interleukin-2-mediated signaling pathway; regulation of T cell tolerance induction; apoptotic process; cell surface receptor signaling pathway; cell surface receptor signaling pathway via JAK-STAT; immune response; positive regulation of activated T cell proliferation; positive regulation of leukocyte differentiation; positive regulation of leukocyte proliferation; inflammatory response to antigenic stimulus; positive regulation of T cell differentiation; positive regulation of T cell proliferation; regulation of immune system process
Cellular component: interleukin-2 receptor complex; external side of plasma membrane; plasma membrane; cell surface; membrane
Genetic constraint (gnomAD): Loss-of-function variants: 25 observed, 38.52 expected, observed/expected ratio (o/e) 0.65, 90% interval 0.47 to 0.91. The upper end of that interval is the gene's LOEUF score, 0.91, which puts it in group 3 of 6, group 1 being the genes least tolerant of losing a copy. Missense variants: 316 observed, 363.21 expected, observed/expected ratio (o/e) 0.87, 90% interval 0.79 to 0.95. Synonymous variants: 125 observed, 120.7 expected, observed/expected ratio (o/e) 1.04, 90% interval 0.89 to 1.2.
Gene-disease validity (ClinGen):
ClinGen rates the evidence that IL2RA causes each of these diseases.
immunodeficiency due to CD25 deficiency (autosomal recessive): Definitive.
Homologues: Orthologues: chimpanzee IL2RA (98% identical), macaque IL2RA (84% identical), rat Il2ra (61% identical), mouse Il2ra (60% identical), guinea pig IL2RA (59% identical), pig IL2RA (57% identical), dog IL2RA (50% identical).
Diseases named in the same sentence as IL2RA in open-access papers:
IL2RA is named in the same sentence as 307 diseases in open-access papers, as found by Europe PMC text mining. Sharing a sentence is not in itself a finding about the gene and the disease. The quoted sentences say what the papers report.
COVID-19 (118 papers, 2020 to 2025). A disease caused by infection with severe acute respiratory syndrome coronavirus 2. "The same trend was observed for IL2RA, a protein involved in leukocyte activation and previously associated with prolonging illness in severe COVID-19 patients." (PMID 38565620, 2024). "In this study, we found ddcfDNA was significantly elevated in SOTRs with COVID-19 and strikingly correlated with cytokines/chemokines (IL-10, IL-8, IL-2Ra, IL-18, GM-CSF and IL-12p70) associated with CRS." (PMID 35075453, 2022). "This study identified 30 nodes associated with cytokine storm, ARDS, and inflammatory process of COVID-19, namely, IL-6, IL-6R, NF-κB, IL-2, IL-2RA, IFNA2, IFNAR1, COX5A, and COX411." (PMID 39640429, 2024). "ILCp cells from COVID-19 patients showed upregulated expression of IL2RA (adj.p = 0.004), IL4R (adj.p = 2.3e-11) as well as other immune-related genes including TNFRSF25 (adj.p = 4.2e-03) and CCR7 (adj." (PMID 39026668, 2024). "In fact, IL2RA+CD4+ T-cells from severe COVID-19 patients expressed Th1, Th2, and IL-10 signature genes more frequently whereas Th17 differentiation was suppressed in IL2RA+ T-cells from both groups." (PMID 33178221, 2020). "These miRNAs target several pro-inflammatory cytokine and chemokine genes (e.g., TNF, CCL2, CXCL9, CXCL10, IL10, VEGFA) as well as cytokine and chemokine receptors and transduction factors (IL1R1, IL2RA, IFNAR2), reported as upregulated and associated with mortality in COVID-19 patients." (PMID 36032130, 2022). "Additionally, IL2RA has been recently identified as significantly upregulated in the plasma of patients with severe COVID-19." (PMID 33924631, 2021). "Previous studies reported that COVID-19 is frequently associated with a massive production of 14 cytokines including IFN-γ, IL-1RA (IL1RN), IL-2RA, IL-6, IL-10, IL-18, HGF, MCP-3 (CCL7), MIG (CXCL9), M-CSF (CSF1), G-CSF (CSF3), MIG-1a (CCL3), CTACK (CCL27), and IP-10 (CXCL10)." (PMID 34262555, 2021). "To functionally test the role of cytokines on the viability of lymphocytes, we treated PBMCs isolated from healthy donors with selected groups of cytokines (e.g., IL-10, IL-15, IL-18, IL-8, IL-6, IL-1RA, IL-2RA, IL-4) for 36 h, using the maximum doses detected in COVID-19 serum." (PMID 34103487, 2021). "Furthermore, IL2RA was significantly upregulated in CD4+ T-cells from severe COVID-19 patients compared to moderately affected patients." (PMID 33178221, 2020). "Importantly, IL2RA expression was significantly increased in severe COVID-19 patients in comparison to moderate patients, whilst very few T-cells expressed IL2." (PMID 33178221, 2020). "Therefore, we suggested that Phaseol may reduce inflammatory cell activation and inflammatory response by acting on CXCL8 and IL2RA, thereby reducing tissue damage from excessive inflammatory response and alleviating the clinical symptoms of COVID-19." (PMID 36120307, 2022). "Six chemokines (CXCL9, CXCL10, CCL4, CCL5, CCL27, and CXCL12) and eight interleukins (IL-1Ra, IL-2Ra, IL-3, IL-5, IL-9, IL-12p40, IL-15, and IL-16) were increased in both PLWH/COVID-19 and COVID-19-only." (PMID 41516165, 2025). "Genes in the subnetwork of the CCL family showed different expression levels in the four groups of COVID-19 severity; in particular, OSM, CCL3, CCL7, and IL2RA showed higher expression in the high-severity COVID-19 samples." (PMID 40362649, 2025). "Together, these findings suggest that IL3 and IL33 contribute to the upregulation of IL2RA and IL2RG on basophils in severe COVID-19." (PMID 41459501, 2025). "Since CD25 (IL2RA) is a key marker for Tregs and activated T-cells, we asked if CD25-expressing T-cells in COVID-19 patients were Tregs." (PMID 33178221, 2020). "Notably, we also observed marked upregulation of IL2RA and IL2RG on basophils in severe COVID-19 patients." (PMID 41459501, 2025). "Therefore, licorice is proposed as an effective candidate for the treatment of COVID-19 through STAT3, IL2RA, MMP1, and CXCL8." (PMID 36120307, 2022).
COVID-19 (continued). "As expected, significantly increased activation of pro-inflammatory cytokines (IL-1α, IL-2Ra, IL-6, IL-8, and IL-18) in fatal COVID-19 compared to non-fatal COVID-19 sera was measured." (PMID 35386707, 2022). "Molecular docking showed that Glycyrol, Phaseol and Glyasperin F in licorice may playe a role in treating COVID-19 by acting on STAT3, IL2RA, MMP1, and CXCL8." (PMID 36120307, 2022). "In this study, Phaseol, Glycyrol and Glyasperin F in licorice may treat COVID-19 to reduce the inflammatory response and promote cell survival by acting on CXCL8, IL2RA, STAT3, and MMP1." (PMID 36120307, 2022). "Focused analysis of 14 cytokines classically upregulated in COVID-19 patients revealed that only some of these cytokines are dysregulated in lung tissue, whereas the other cytokines are upregulated in extrapulmonary tissues (e.g. IL6 and IL2RA)." (PMID 34262555, 2021). "Moreover, a study using bioinformatics analysis and molecular dynamic stimulation has shown that phaseol in licorice may have beneficial effects in reducing the inflammatory response to COVID-19 by inhibiting the activation of CXCL8 and IL2RA." (PMID 36873992, 2023). "Therefore, the active small molecules Phaseol, Glycyrol and Glyasperin F in licorice may act on CXCL8, IL2RA, STAT3, and MMP1 to treat COVID-19 by reducing tissue damage and inflammatory response." (PMID 36120307, 2022). "The induction by estrogen and androgen of ACE2, and possibly of IL2RA, established a negative correlation between ACE2 expression, age of the subjects and COVID-19 fatality at both population and molecular levels." (PMID 32268515, 2020).
autoimmune disease (66 papers, 2009 to 2025). A disorder resulting from loss of function or tissue destruction of an organ or multiple organs, arising from humoral or cellular immune responses of the individual to their own tissue constituents. "We previously performed CRISPR FACS-based screens in primary human T cells to identify the upstream regulators of IL2RA, an important cell surface receptor implicated in numerous autoimmune diseases 3,18,19." (PMID 38948774, 2024). "It has been shown that the IL2RA locus is associated with other autoimmune diseases like systemic lupus erythematosus and ANCA-associated systemic vasculitis." (PMID 37626706, 2023). "The association of IL2RA locus with various autoimmune diseases suggests that the IL2RA pathway plays an important but still undefined role in each of these diseases." (PMID 37626706, 2023). "The gene locus of IL2RA has been ascertained as a risk factor for a diverse series of autoimmune diseases, including SLE." (PMID 36435781, 2022). "We chose IL2RA because of its known association with a broad spectrum of autoimmune diseases, including JIA, and IL6R because this locus does not appear on GWAS for any other autoimmune disease and, thus, its effects appear to be specific for JIA." (PMID 32730263, 2020). "The high levels of IL2RA in activated circulating immune cells and Tregs is exploited for IL-2 immunotherapy of tumors and autoimmune diseases; and certain polymorphisms of IL2RA are related to the risk of kidney cancer." (PMID 32983989, 2020). "IL2RA deficient mice shows a complete deficiency of regulatory T cells and develop multiorgan lethal autoimmune disease involving skin, intestine, lung, and liver." (PMID 31616649, 2019). "SNPs of the IL2RA locus significantly associated with two or more autoimmune diseases according to GRASP database." (PMID 28234966, 2017). "Given our prior interest in the potential for autoimmune-disease associated genetic variants to regulate IL2RA expression, we were interested to note PCHi-C interactions between some of these variants and the IL2RA promoter." (PMID 28870212, 2017). "Variants in IL2RA are also associated with the risk of development of RA and other autoimmune diseases such as MS and type 1 DM." (PMID 26350950, 2015). "Given the importance of Treg in tolerance and known defects in Treg of T1D and MS subjects, it is likely that decreased stability and function of Treg is a major mechanism by which IL2RA variants contribute risk in associated autoimmune diseases." (PMID 24376757, 2013). "The alpha-chain of the receptor for IL2 (IL2RA) is a risk gene for MS and other autoimmune diseases." (PMID 20856809, 2010). "The association of IL2RA/CD25 with a fifth autoimmune disease suggests that this gene, along with the PTPN22 gene, appears to play a vital role in immune regulation and function as well as predisposition to autoimmunity in general." (PMID 19116909, 2009). "Current publications showed association between autoimmune diseases and chromosome 10p15 region for IL2RA (interleukin 2 receptor-α), chromosome 2q33 region for CTLA-4 (cytotoxic T-lymphocyte antigen-4) and chromosome 2q24 region for IFIH1 (interferon induced with helicase C domain 1)." (PMID 32974248, 2020). "Variants of IL2RA gene had been recently associated with susceptibility to several autoimmune diseases such as T1D, AITDs, rheumatoid arthritis or juvenile idiopathic arthritis that implies the possible general effect on predisposition to autoimmunity of this region." (PMID 32974248, 2020). "SNPs of genes influencing Treg function, such as IL2RA, may cause an increased risk of autoimmune disease." (PMID 32974248, 2020). "Therefore, various fine-mapping strategies have been developed and we chose IL2RA as an example to illustrate how fine-mapping strategies have helped to define candidate causal variants for several autoimmune diseases." (PMID 30060490, 2018).
autoimmune disease (continued). "Multiple variants in and near IL2RA have been associated with a number of autoimmune diseases." (PMID 28870212, 2017). "Another interesting gene is interleukin-2 receptor alpha (IL2RA); variants in IL2RA have shown to be associated with a decreased risk for development of RA and for the development of other autoimmune diseases such as multiple sclerosis (MS) and diabetes mellitus (DM)." (PMID 26350950, 2015). "The association of IL2RA polymorphisms with autoimmunity is more complex and a given polymorphism may show the opposite effect in different autoimmune disorders." (PMID 23676143, 2013). "Differential association of autoimmune diseases and SNPs within the IL2RA locus suggests that the IL2RA pathway may prove to play differing, as yet undefined, roles in each disease." (PMID 19265545, 2009). "Genome-wide association studies (GWAS) have already identified shared susceptibility loci across multiple autoimmune diseases, including variants in HLA regions, CTLA4, and IL2RA, suggesting common immunoregulatory pathways." (PMID 40787461, 2025). "A CRISPR activation screen identified a risk variant in an enhancer region of the IL2RA gene and more recently MPRA was used to prioritize approximately 18,000 autoimmune disease associated-variants based on how they perturb regulatory elements in T cells." (PMID 35979360, 2022). "This non-coding variant is found within an intron of interleukin-2 receptor alpha (IL2RA) and is associated with multiple autoimmune diseases, including type 1 diabetes (T1D) and RA." (PMID 34508276, 2022). "Animal experiments have also shown that mutations of genes in certain susceptibility loci including Il2, Il2ra (CD25), Ctla4, PTPN22, and Pdca1 (PD-1) significantly increase the susceptibility for a number of autoimmune diseases, including T1DM." (PMID 35159301, 2022). "Here we demonstrated the contribution of polymorphic variants of genes encoding IL2RA, CTLA-4, and IFIH1 to autoimmune diseases predisposition." (PMID 32974248, 2020). "Four genes CTLA4, IL2RA, ICOS, and IL7R have been associated with a group of autoimmune diseases in GWAS and with autoimmunity in the HPO database." (PMID 31695696, 2019). "Genetic studies in autoimmune disease identified polymorphisms in IL-2 pathway genes encoding IL-2RA (CD25), IL-2, CTLA-4 and PTPN2 as key drivers in autoimmune disease susceptibility." (PMID 30446251, 2018). "Tregs are a population of T cells characterized by the expression of CD25 (IL-2Ra) and the transcription factor Foxp3, and their general role has been demonstrated as immunosuppressive in various experimental settings of autoimmune diseases." (PMID 28280495, 2017). "Understanding if altered IL-2R signaling is a phenotype common to multiple autoimmune diseases and how this relates to the genetic heterogeneity at the IL2RA locus is important for elucidating mechanisms common or unique to associated autoimmune diseases." (PMID 24376757, 2013). "We therefore genotyped autoimmune disease-prone variants of the IL2RA region (rs11594656, rs41595061 and rs2104286) in two distinct autoimmune diseases associated with soluble IL-2RA elevation, using three independent SLE cohorts and one AAV cohort." (PMID 19265545, 2009). "The SNP, rs2104286, has also been associated recently with T1D, representing a third independent effect for the IL2RA region in this autoimmune disease." (PMID 19265545, 2009). "Importantly, ROMO1 and IL2RA (Cor = -0.73, P < 0.001) exhibited significant correlations in autoimmune diseases." (PMID 40254686, 2025). "In addition, another novel gene, IL2RA interacts with the well-known autoimmune disease genes CCR6, IRF5, and CD40, which are the hub genes in the network." (PMID 38360850, 2024).